SPOP (speckle type BTB/POZ protein)
Diseases named in the same sentence as SPOP in open-access papers (continued):
Sharing a sentence is not in itself a finding about the gene and the disease.
prostate carcinoma (continued). "HDAC3 knockdown or blockade causes the impaired growth of prostate cancer organoids and xenografts in the context of PTEN deletion or SPOP mutation." (PMID 36768610, 2023). "Prostate cancer-associated mutations, such as W131F and F133V, within the MATH domain of SPOP have been found to disrupt the interaction between SPOP and DAXX." (PMID 37705755, 2023). "Recent studies found that SPOP mutations and CHD1 deletion sensitize prostate cancer cells to DNA damage inducers and show synergistic effects on the DNA damage repair." (PMID 36776288, 2023). "SPOPL deletion is found in The Cancer Genome Atlas prostate cancers, comparable to SPOP deletion in prostate cancer." (PMID 36769824, 2023). "Consistently, it has been revealed that SPOP serves as a tumor repressor gene in gastric, colorectal, and prostate cancers." (PMID 35461336, 2022). "Prostate cancer-associated SPOP mutants display impaired binding to BET proteins, leading to reduced proteasomal degradation and accumulation of the protein in prostate cancer cell lines and patient specimens, and causing resistance to BET inhibitors." (PMID 36171897, 2022). "Cancer genome characterizations have identified missense variations in the SPOP gene in 11~13% of primary prostate cancer and 6~8% of metastatic, castration-resistant prostate cancers (CRPC)." (PMID 36115849, 2022). "Recently it has been discussed that SPOP actually has a dual role, and while being a tumour suppressor in prostate cancer it performs as an oncogene in kidney cancer." (PMID 35975235, 2022). "SPOP was regarded to be a tumor suppressor in many cancers, like prostate cancer, colorectal cancer, breast cancer, and endometrial cancer (PMID: 31,771,591; 31,772,275; 31,911,863)." (PMID 35773729, 2022). "Resistance to BET inhibitors in SPOP-mutant prostate cancer can be overcome by combination with AKT inhibitors and further supports the evaluation of SPOP mutations as biomarkers to guide BET inhibitor-directed therapy in prostate cancer patients." (PMID 36171897, 2022). "Importantly, a publication has reported that the loss-of-function mutation in SPOP compromises ubiquitination-mediated PD-L1 degradation, thus increasing PD-L1 level and reducing the number of tumor-infiltrating lymphocytes in mouse tumors and in clinical prostate cancer specimens." (PMID 35461336, 2022). "They used this model to simulate numerous prostate cancer molecular changes, including but not limited to TMPRSS2-ERG fusion, SPOP mutation, SPINK1 overexpression, and CHD1 loss." (PMID 35813047, 2022). "The study reveals a new way of SPOP inactivation and provides an opportunity for precision intervention against G3BP1high prostate cancer." (PMID 35252555, 2022). "The data suggest a therapeutic opportunity for SPOP inhibition or high-dose androgen therapy in prostate cancers that express high levels of ERG." (PMID 33531470, 2021). "We demonstrate that the SPOP-ITCH signaling pathway plays a critical role in prevention of prostate cancer metastasis." (PMID 34322378, 2021). "elucidated the tumor suppressor role of SPOP in prostate cancer, in which it promoted the degradation of the bromodomain and extraterminal (BET) proteins to further impact the treatment effectiveness of BET inhibitors." (PMID 34838022, 2021).
prostate carcinoma (continued). "We used siRNA to suppress the SPOP expression in prostate cancer cells, and performed a mass spectrometry analysis on the lysates from these cells to determine which proteins have an altered expression upon the depletion of SPOP." (PMID 34322378, 2021). "While the role of SPOP protein differs depending on the tumor type, in prostate cancer, SPOP seems to function as a tumor suppressor and its targets for degradation, among others, include AR, ERG, steroid receptor coactivator 3 (SRC3), BRD4, MYC, and TRIM24." (PMID 33572160, 2021). "As a connection to the ubiquitination pathway in prostate cancer, it was shown that SPOP promotes cellular senescence by degrading the SENP7." (PMID 33572160, 2021). "The study reveals an upstream regulatory pathway of SPOP inactivation and sheds light on another intervention strategy against prostate cancer." (PMID 34795264, 2021). "The molecular mechanism underlying the DNA hypermethylation phenotype observed in the SPOP-mutant prostate cancers is unclear." (PMID 34588438, 2021). "TRIM28 prevented TRIM24 from SPOP-mediated degradation, promoting the progression of prostate cancer." (PMID 34722282, 2021). "For example, when compared to prostate cancers from predominantly White men, prostate cancers from Black men contain fewer TMPRSS2-ERG fusions, fewer PTEN deletions, and more SPOP mutations." (PMID 34191807, 2021). "Here, the authors show that mutant SPOP induces global aberrant DNA methylation patterns through GLP/G9a and renders prostate cancer cells susceptible to DNA demethylating agents." (PMID 34588438, 2021). "Immunohistochemistry (IHC) staining was used to study the expression of PDK1 and SPOP in prostate cancer tissues." (PMID 34353330, 2021). "Potentially actionable genomic lesions in the tumor were identified through a personalized medicine approach for potential future therapy, but at the moment, he remains in remission, illustrating the hormonal sensitivity of his SPOP-driven prostate cancer." (PMID 33568750, 2021). "Co-immunoprecipitation (co-IP) assays confirmed that both ectopically expressed and endogenous SPOP interacted with Geminin in 293T cells and PC-3 prostate cancer cells." (PMID 34599168, 2021). "In prostate cancer, recurrent gene fusions involving the ERG transcription factor and point mutations in the ubiquitin ligase adaptor SPOP are two truncal mutations that are mutually exclusively distributed across tumor genomes 3–9." (PMID 33531470, 2021). "The interaction between TRIM28 and TRIM24 protects TRIM24 from SPOP-mediated ubiquitin degradation and promotes the progression of prostate cancer." (PMID 34330324, 2021). "Speckle-type POZ protein (SPOP), which is one of the most frequently mutated genes in prostate cancer, is an adapter that brings INF2 and other substrates to the proximity of specific E3 ubiquitin ligase complexes for ubiquitination." (PMID 34685534, 2021). "Previous studies have shown that TRIM28 protects TRIM24 from SPOP-mediated ubiquitin degradation and promotes the progression of prostate cancer." (PMID 34330324, 2021). "SPOP functions as a tumour suppressor in prostate cancer but how the protein is regulated is unclear." (PMID 34795264, 2021). "In SPOP-mutant prostate cancer, several dysregulated SPOP substrates (e.g., NCOA3, TRIM24, BET proteins) have been shown to boost the AR pathway leading ultimately to high levels of AR target genes 3,13,19–26." (PMID 33531470, 2021). "We began our validation by using siRNA to knockdown SPOP expression in prostate cancer cells followed by measuring the expression of ITCH by Western blot." (PMID 34322378, 2021).
prostate carcinoma (continued). "Similar to tumour TL, the TL ratio did not significantly differ between samples with any of the recurrent prostate cancer-related GRs or CNAs but samples with a somatic SNV in the gene SPOP had smaller TL ratios." (PMID 34824250, 2021). "Owing to its role in regulating drivers of oncogenesis, SPOP has emerged as a potent tumor suppressor in prostate cancer." (PMID 34322378, 2021). "As a tumor suppressor, SPOP mutations occur around 15% in prostate cancer, and display a mutual exclusion with PTEN deletion/mutations, indicating the potential connection of SPOP status and the PI3K-AKT signaling pathway." (PMID 34353330, 2021). "Together our data highlight the role of the SPOP-ITCH axis in protection against prostate cancer metastasis." (PMID 34322378, 2021). "Together, our results highlight the functional significance of the SPOP-ITCH pathway in prostate cancer metastasis." (PMID 34322378, 2021). "To functionally analyze androgen deprivation or the antiandrogen enzalutamide response, we chose to ectopically express different SPOP variants and ΔERG in the androgen-dependent human LAPC4 prostate cancer cells that are wild-type for both driver genes." (PMID 33531470, 2021). "In echoing this finding, we detected PDK1 expression in prostate cancer patients, and observed that samples of SPOP mutants displayed a relative higher PDK1 expression compared with that of samples harboring intact SPOP." (PMID 34353330, 2021). "In the present study, we sequenced the SPOP gene in a cohort of 198 prostate cancer patients in China." (PMID 34322378, 2021). "Here, we have identified G3BP1 as an interactor of SPOP and functions as a competitive inhibitor of Cul3SPOP, suggesting a distinctive mode of Cul3SPOP inactivation in prostate cancer (PCa)." (PMID 34795264, 2021). "We also examined the effect of ATR inhibition by VE-822 in a clinically-relevant setting by using the SPOP Q165P mutant patient-derived xenograft (PDX) model established from a prostate cancer metastatic lesion." (PMID 34599168, 2021). "The WGS analysis showed that gene rearrangements were detected more frequently in prostate cancers expressing SPOP mutants (n = 383) than in those expressing wild-type SPOP (n = 47)." (PMID 33023230, 2020). "The accumulation of γH2AX by SPOP knockdown was observed in prostate cancer cell lines that were AR-positive (LNCaP cells, C4-2 cells), but not in those that were AR-negative (PC3 cells, DU145 cells)." (PMID 33023230, 2020). "Our results indicate a strong association between low ZBTB38 expression in localised tumours with heightened levels of chromosomal instability as well as mutations of SPOP, which reinforce the association of ZBTB38 with aggressive prostate cancer." (PMID 32365491, 2020). "SPOP knockdown in various prostate cancer cell lines (e.g., C4-2b cells, PC3 cells, LNCap cells, 22Rv1 cells) or U2OS cells reduced the mRNA and protein expression of ATR, BRCA2, ChK1, and Rad51." (PMID 33023230, 2020). "Since most studies focus on the function and molecular mechanisms of SPOP in prostate cancer, the detailed role of SPOP in other tumors must be explored." (PMID 31901237, 2020). "Thus, the prostate cancer-associated SPOP mutants could exert dominant-negative effects." (PMID 33023230, 2020). "Particularly, SPOP inhibits the self-renewal and stem cell properties of prostate cancer cells via the ubiquitinating-dependent degradation of NANOG regulated by AMPK activation or by direct interaction with NANOG." (PMID 31366128, 2019). "A series of functional analyses in cell lines, patient samples, and xenograft models were performed to investigate the biological significance and clinical relevance of SPOP regulation of SG signaling in prostate cancer." (PMID 31771591, 2019).
prostate carcinoma (continued). "Gene fusions involving E26 transformation-specific (ETS) family members and coding mutations mainly affecting speckle-type POZ protein (SPOP), forkhead box protein A1 (FOXA1), and isocitrate dehydrogenase 1 (IDH1) are found in primary prostate cancer." (PMID 31200487, 2019). "These suggest that SPOP mutants in prostate cancer have less activity to promote CYCLIN E1 degradation." (PMID 30237511, 2019). "Knockout of SPOP or expression of prostate cancer-associated SPOP mutants conferred resistance to death caused by SG inducers (e.g. docetaxel, sodium arsenite and H2O2) in prostate cancer cells." (PMID 31771591, 2019). "Depletion of SPOP by short hairpin RNA (shRNA)-mediated knockdown or CRISPR/Cas9-mediated knockout in multiple prostate cancer cell lines resulted in a marked increase in the steady-state levels of endogenous Caprin1)." (PMID 31771591, 2019). "Caprin1 abundance is elevated in SPOP-mutant expressing prostate cancer cell lines and patient specimens." (PMID 31771591, 2019). "Despite high PSA pretreatment values, the SPOP-mutant prostate cancers have a favorable prognosis with improved metastasis-free survival, especially in patients exhibiting high PSA pretreatment levels." (PMID 31366128, 2019). "Our findings obtained from novel SPOP‐mutated prostate cancer PDX and organoid models stress that prostate cancers, especially SPOP‐mutated subtype, can be effectively treated by the BET and CBP/p300 dual inhibitor." (PMID 31559706, 2019). "Docetaxel, the most commonly-used therapeutic drug in prostate cancer, induced much more SGs in SPOP knockdout cells but less SGs in Caprin1 knocout cells compated with that in control cells." (PMID 31771591, 2019). "Altogether, we have revealed a novel mechanism for SPOP in suppressing prostate cancer and provided evidence to show SPOP has dual functions in prostate cancer and CCRC." (PMID 30237511, 2019). "In prostate cancer, ELOVL2 showed a notable upregulation in SPOP mutations that mediate drug resistance." (PMID 31856871, 2019). "Resistance rooted from SPOP mutations and NCOR2 deficiency appears cancer-type specific to prostate cancer because SPOP mutations in endometrial cancer sensitize BET inhibitor, an effect converse in prostate cancer." (PMID 31311566, 2019). "CYCLIN E1 expression rescued proliferation, migration, and tumor formation of prostate cancer cell suppressed by SPOP." (PMID 30237511, 2019). "Upregulation of DUB3 induced by nuclear receptor corepressor 2 (NCOR2) gene deletion in prostate cancer leads to BET inhibitor resistance resulting from elevated BRD4, which converges with SPOP mutation." (PMID 31311566, 2019). "For example, SPOP acts as a cancer suppressor in prostate cancer by promoting the proteasomal degradation and ubiquitination of the SRC-3 (p160 steroid receptor coactivator-3) protein, thus suppressing androgen receptor transcription activity." (PMID 30607139, 2018). "SPOP mutations and ERG rearrangements show near complete mutual exclusivity across multiple independent cohorts representing thousands of prostate cancer samples." (PMID 29202479, 2018). "Previous studies showed that SPOP inactivation increased cell proliferation, migration and invasion in prostate cancer cell lines." (PMID 29996942, 2018).
prostate carcinoma (continued). "Our results showed that prostate cancer-derived SPOP mutants including Y87C, F102V, W131G, and F133L, which are located in its substrate-recognizing MATH domain, failed to bind to and promote HDAC6 degradation." (PMID 28599312, 2017). "Previous studies showed that SPOP inactivation increased cell proliferation primarily in AR-positive prostate cancer cells, but increased prostate cell migration and invasion in an AR-independent manner." (PMID 28448495, 2017). "In summary, PRISM-SRM enables multiplexed, isoform-specific detection of mutant SPOP proteins in cell lysates, providing significant potential in biomarker development for prostate cancer." (PMID 28810879, 2017). "Our results showed that deletion of the NLS sequence forced prostate cancer-associated SPOP mutants to localize in cytosol as puncta, but these mutants cannot alter the ER localization of INF2 like SPOP-WT." (PMID 28448495, 2017). "SPOP inactivation-induced prostate cancer cell migration and invasion is partly mediated by INF2 and mitochondrial fission." (PMID 28448495, 2017). "Further, the transcriptional activator tripartite motif-containing 24 (TRIM24) is stabilized by speckle-type POZ protein (SPOP) mutations, which are often detected in recurrent prostate cancer." (PMID 28486411, 2017). "Since these two types of genetic alterations, i.e., SPOP mutations and TMPRSS2-ERG fusions, similarly lead to ERG stabilization, it is conceivable that their incidences are mutually exclusive in prostate cancers." (PMID 27200299, 2016). "Mutations in the substrate recognition domain of the CRL CUL3 adaptor speckle-type POZ protein (SPOP) are frequently found in primary prostate cancer." (PMID 27379159, 2016). "Among them, DEK stabilization contributes to prostate cancer invasion and stem cell-like property and DEK upregulation correlates with SPOP mutations, in prostate cancer." (PMID 27200299, 2016). "Collectively, SPOP targets the degradation of multiple tumor-promoting proteins in prostate cancer to contribute to the carcinogenesis process." (PMID 27200299, 2016). "Consistent with increased intrachromosomal rearrangements, SCNA analysis revealed that SPOP mutant prostate cancers showed significantly higher total copy number alteration burden." (PMID 26374986, 2015). "The drugs, which have been recently tested successfully in patients with prostate cancer, block a different method of DNA repair that operates separately to the one that involves SPOP." (PMID 26374986, 2015). "Taken together, these results suggest that SPOP promotes HDR, while somatic mutation in SPOP, as observed in prostate cancer with increased genomic rearrangements, impairs HDR and promotes error-prone NHEJ." (PMID 26374986, 2015). "Reduction of SPOP expression increased the sensitivity of these prostate cancer cells to both PARP inhibitors." (PMID 26374986, 2015). "Recently, DEK was identified as an SPOP substrate that exhibited decreases in ubiquitylation and proteasomal degradation and increase in expression in SPOP-mutant prostate cancer." (PMID 25544761, 2015). "Intriguingly, SPOP mutations (function to stabilize AR) and TMPRSS2-ETS translocations are mutually exclusive in prostate cancer." (PMID 24508459, 2014). "SRC-3, a coactivator of AR that is often upregulated in prostate cancer, is another SPOP ubiquitination target." (PMID 24508459, 2014). "We demonstrated that SPOP promotes AR degradation and inhibits the transcriptional activity of the AR and AR-mediated prostate cancer proliferation." (PMID 24508459, 2014). "Together, these findings suggest that SPOP promotes AR protein ubiquitination and proteasome degradation and inhibits prostate cancer cell growth in an AR-dependent manner." (PMID 24508459, 2014). "Knockdown of endogenous SPOP by two independent SPOP-specific small interfering RNAs (siRNAs) increased AR protein levels in both LNCaP and C4-2 prostate cancer cells." (PMID 24508459, 2014).